RN7SL817P (RNA, 7SL, cytoplasmic 817, pseudogene)
Gene: Miscellaneous RNA gene on chromosome 2 (46,448,224 to 46,448,511, reverse strand). Ensembl gene ENSG00000241791.
Homologues: Orthologues: chimpanzee Metazoa_SRP (98% identical), macaque Metazoa_SRP (88% identical). Paralogues in human: RN7SL2 (82% identical), RN7SL1 (82% identical), RN7SL3 (81% identical), RN7SL220P (79% identical), RN7SL126P (79% identical), RN7SL597P (79% identical), RN7SL680P (79% identical), RN7SL732P (79% identical), RN7SL147P (78% identical), RN7SL357P (78% identical), RN7SL448P (78% identical), RN7SL203P (78% identical), and 704 more.